FXYD3 (FXYD domain containing ion transport regulator 3)
Description:
Associates with and regulates the activity of the sodium/potassium-transporting ATPase (NKA) which transports Na(+) out of the cell and K(+) into the cell. Reduces glutathionylation of the NKA beta-1 subunit ATP1B1, thus reversing glutathionylation-mediated inhibition of ATP1B1. Induces a hyperpolarization-activated chloride current when expressed in Xenopus oocytes. [Isoform 1]: Decreases the apparent K+ and Na+ affinity of the sodium/potassium-transporting ATPase over a large range of membrane potentials. [Isoform 2]: Decreases the apparent K+ affinity of the sodium/potassium-transporting ATPase only at slightly negative and positive membrane potentials and increases the apparent Na+ affinity over a large range of membrane potentials.
Synonyms: MAT8; PLML; MAT-8
Tractability: Antibody: UniProt places it where antibodies can reach, with high confidence; its Gene Ontology location is reachable by antibodies, with high confidence; UniProt predicts a signal peptide or a membrane-spanning region; the Human Protein Atlas places it where antibodies can reach.
Gene: Protein-coding gene on chromosome 19 (35,115,521 to 35,125,653, forward strand). Ensembl gene ENSG00000089356.
Subcellular location: Cell membrane
Subcellular location (Human Protein Atlas): Nucleoplasm; Plasma membrane
Pathways (Reactome):
Disease: Potential therapeutics for SARS
Muscle contraction: Ion homeostasis
Transport of small molecules: Ion transport by P-type ATPases
Gene Ontology:
Molecular function: chloride channel activity; sodium channel regulator activity; ATPase binding; ion channel regulator activity
Biological process: chloride transport; establishment or maintenance of transmembrane electrochemical gradient; intracellular potassium ion homeostasis; intracellular sodium ion homeostasis; positive regulation of sodium ion export across plasma membrane; potassium ion import across plasma membrane; proton transmembrane transport; sodium ion export across plasma membrane; chloride transmembrane transport; regulation of monoatomic ion transport
Cellular component: extracellular exosome; plasma membrane; sodium:potassium-exchanging ATPase complex; endoplasmic reticulum membrane; membrane
Genetic constraint (gnomAD): Loss-of-function variants: 13 observed, 19.76 expected, observed/expected ratio (o/e) 0.66, 90% interval 0.43 to 1.05. The upper end of that interval is the gene's LOEUF score, 1.05, which puts it in group 4 of 6, group 1 being the genes least tolerant of losing a copy. Missense variants: 101 observed, 113.99 expected, observed/expected ratio (o/e) 0.89, 90% interval 0.75 to 1.04. Synonymous variants: 48 observed, 40.69 expected, observed/expected ratio (o/e) 1.18, 90% interval 0.94 to 1.5.
Homologues: Orthologues: chimpanzee FXYD3 (99% identical), macaque FXYD3 (91% identical), guinea pig FXYD3 (74% identical), mouse Fxyd3 (74% identical), rat Fxyd3 (74% identical), pig FXYD3 (72% identical), dog FXYD3 (71% identical), tropical clawed frog fxyd3 (49% identical). Paralogues in human: FXYD4 (55% identical), FXYD6 (37% identical), FXYD1 (32% identical), FXYD5 (26% identical), FXYD7 (24% identical), FXYD2 (23% identical).
Diseases named in the same sentence as FXYD3 in open-access papers:
FXYD3 is named in the same sentence as 45 diseases in open-access papers, as found by Europe PMC text mining. Sharing a sentence is not in itself a finding about the gene and the disease. The quoted sentences say what the papers report.
breast cancer (20 papers, 2007 to 2025). A primary or metastatic malignant neoplasm involving the breast. "While increased expression of FXYD3 has been associated with breast cancer, the factors that promote up-regulation of this protein in mammary cells have not been identified." (PMID 26090296, 2015). "FXYD3 is overexpressed in various tumours including human breast cancer, bladder cancer, prostate carcinoma, rectal cancer, gastric adenocarcinoma, intrahepatic cholangiocarcinoma and hepatocellular carcinoma." (PMID 39783776, 2025). "FXYD3 (antigen-8 of mammary tumor) is known to exert protection of the β1 subunit against glutathionylation, an oxidative modification that destabilizes the α-β heterodimer and inhibits Na, K–ATPase activity." (PMID 39769162, 2024). "FXYD3, an mRNA also known as Mat-8 (Mammary tumor 8 kDa), is highly expressed in breast cancers and has been shown to regulate breast cancer stem cells." (PMID 37345113, 2023). "FXYD3-pep SKSK reproduced the increase in doxorubicin-induced cytotoxicity seen after FXYD3 siRNA transfection in pancreatic- and breast cancer cells that overexpressed FXYD3, while FXYD3-pep CKCK boosted the native protein’s protection against doxorubicin." (PMID 35371992, 2022). "The chemotherapeutic doxorubicin induces oxidative stress, and suppression of FXYD3 with siRNA in pancreatic- and breast cancer cells that strongly express FXYD3 increased doxorubicin-induced cytotoxicity." (PMID 35371992, 2022). "Suppression of FXYD3 with siRNA in cultured human breast cancer cells that overexpress FXYD3 augments cytotoxicity of doxorubicin (Dox)." (PMID 35371992, 2022). "FXYD3 has been reported to be highly expressed in several types of cancers, including breast cancer, and is related to the survival rate and metastasis." (PMID 33621431, 2021). "FXYD3 was found to be upregulated in several cancers, such as hepatocellular carcinoma, pancreatic cancer, endometrial cancer and breast cancer." (PMID 34270462, 2021). "FXYD domain containing ion transport regulator 3 (FXYD3), also named as mammary tumor 8, is a part of FXYD protein family and mainly distributed in cell membrane and cytoplasm." (PMID 32432654, 2020). "Previous investigations have revealed the aberrant expression of FXYD3 in diverse cancers, including prostate cancer, colorectal cancer, esophageal squamous carcinoma, breast cancer, pancreatic cancer, glioma and lung cancer." (PMID 32432654, 2020). "This gene has different expression levels in breast cancer cells with different proliferative and differential potentials, validating the distinctive expression levels of Fxyd3 in different cancer cell subtypes." (PMID 33584803, 2020). "Our study provides the first primary evidence of estrogen and the SERM tamoxifen serving as up-regulators of FXYD3 on human breast cancer cells." (PMID 26090296, 2015). "Our observations provide the first evidence of a mechanism through which estrogen can serve to up-regulate FXYD3 in human breast cancer cells." (PMID 26090296, 2015). "Our future studies will focus on the mechanisms through which these factors influence expression of FXYD3 on human breast cancer cells, and analysis of how such changes in FXYD3 evoked by estrogen or tamoxifen affect proliferative activity of these cells." (PMID 26090296, 2015). "Ongoing research endeavors are focusing on identifying cellular components through which estrogen and tamoxifen, alone or in combination, differentially regulate FXYD3 expression in human breast cancer cells." (PMID 26090296, 2015). "Ongoing research efforts are focusing on determining what specific transcriptional factors are involved in the regulation of FXYD3 expression in breast cancer cells by estrogen, tamoxifen, and the combination of these agents." (PMID 26090296, 2015). "FXYD3 expression is upregulated in breast cancer tissues and cancer cell lines, intrahepatic cholangiocarcinoma, thyroid cancer, colon cancer, certain prostate cancer cells and in urothelial cancers." (PMID 25013464, 2014).
breast cancer (continued). "However, given that siRNA‐induced suppression of FXYD3 in breast cancer cells that overexpress FXYD3 amplifies effects of doxorubicin or γ‐radiation on cell death and apoptosis, overexpression of FXYD3 is a potentially useful treatment target." (PMID 39783776, 2025). "With this in mind, we examined whether exposure of cells to estrogen, alone or in combination with tamoxifen, could regulate FXYD3 expression in human breast cancer cells." (PMID 26090296, 2015). "We evaluated whether estrogen and the selective estrogen receptor modulator tamoxifen could regulate the expression of FXYD3 on breast cancer cells." (PMID 26090296, 2015). "Our results indicate that there may be two mechanisms, both involving ER α and one requiring ZEB1, through which FXYD3 may be increased by estrogen and tamoxifen in breast cancer cells." (PMID 26090296, 2015). "Increased expression of the FXYD3 family of proteins has been associated with lung, colorectal, bladder and pancreatic cancers, and recent evidence suggests that elevated FXYD3 may promote tumor cell proliferation in breast cancer as well." (PMID 26090296, 2015). "Our observation that estrogen and tamoxifen could serve to increase FXYD3 expression in breast cancer cells prompted us to examine potential mechanisms through which this increased gene expression might be occurring." (PMID 26090296, 2015). "We were able to show that FXYD3 and PTX3 expression is associated with poor overall patient survival in SCC patients and LAD1, SLC7A5, SLPI, NID2, SPOCK1 and SULF1 correlated significantly with impaired pCR in breast cancer patients." (PMID 23251436, 2012). "The role of FXYD3 in malignancy has been investigated in a variety of cancers, including esophageal squamous cell carcinoma, gastric cancer, endometrial cancer, pancreatic cancer, breast cancer, hepatocellular carcinoma, glioma, lung cancer, and colorectal carcinoma." (PMID 35892856, 2022). "Specifically, module I is highly activated in the six DCIS areas identified in the original study, representing the spatial expression of breast cancer markers such as SPINT2, FXYD3, and ERBB2." (PMID 40033360, 2025). "Similar to the distribution of overexpressed WT FXYD3 in resected pancreatic and breast cancers, we detected TRITC-tagged FXYD3-pep SKSK intracellularly, predominately in a perinuclear distribution." (PMID 35371992, 2022). "In breast cancer, the SOX9/FXYD3/Src axis is critical for promoting cancer stem cell function and tamoxifen resistance." (PMID 34270462, 2021). "We report in the results of our current study that both estrogen and the SERM tamoxifen can significantly increase the expression of FXYD3 in ER α-positive, MCF-7 human breast cancer cells." (PMID 26090296, 2015). "Analysis of The Cancer Genome Atlas database showed that FXYD3 was upregulated in breast cancer tissues and not in normal tissues, and breast cancer patients with high FXYD3 expression showed poor prognosis." (PMID 37966117, 2023). "FXYD3-pep SKSK did not augment the effect of Dox on pancreatic Panc-1 cells that do not express FXYD3 or on the breast cancer cell line MDA-MB-468 that expresses FXYD3 at a low level." (PMID 35371992, 2022). "We set out to evaluate whether estrogen and tamoxifen could affect the expression of FXYD3 or E-cadherin on the surface of MCF-7 and 231 breast cancer cells." (PMID 26090296, 2015). "Furthermore, GPRC5A together with FXYD domain-containing ion transport regulator 3 (FXYD3) and PYCARD have been reported as potential predictors of pathological grading of breast cancer and might benefit the management of clinical treatments." (PMID 30417009, 2018). "However, factors involved in up-regulating the expression of FXYD3 in breast cancer have not been identified." (PMID 26090296, 2015).
breast cancer (continued). "From the downregulated genes of the EMT-core gene list, low FXYD3 expression showed a trend to poor overall survival of SCC patients (p = 0.17) and low expression of LAD1 (p = 0.00074), SLC7A5 (p = 0.0093) and SLPI (p = 0.043) significantly correlated with worse pCR of breast cancer patients." (PMID 23251436, 2012). "However, how FXYD3 contributes to the proliferation of differentiated non-CSCs and which isoform plays a greater role in patient-derived breast cancer cell proliferation remain largely unknown." (PMID 37966117, 2023).
pancreatic cancer (10 papers, 2014 to 2026). "The high expression of FXYD3 was linked to a bad prognosis for patients with pancreatic cancer and stimulated the growth, invasion, and migration of pancreatic cancer cells." (PMID 39682235, 2024). "A peptide‐drug derived from the Cys‐mutated FXYD3 peptide potentially might sensitise highly prevalent pancreatic cancers overexpressing FXYD3 to systemic therapies." (PMID 39783776, 2025). "FXYD3 is a transmembrane protein overexpressed in numerous cancers including pancreatic cancer and, like other seven members of the FXYD family, is known to modulate Na/K‐ATPase activity." (PMID 39783776, 2025). "BxPC-3 pancreatic cancer cells which have high FXYD3 expression were treated with siRNA transfection to modulate FXYD3 expression." (PMID 35371992, 2022). "Studies on pancreatic cancer show that FXYD3 expression in cancerous tissues and pancreatic cancer cell lines is significantly higher than in normal pancreatic tissues and in chronic pancreatitis." (PMID 25013464, 2014). "FXYD3 could be a biomarker for early-stage pancreatic cancer." (PMID 39682235, 2024). "With the high prevalence of FXYD3 expression in PDAC shown here, there might also be significant scope for FXYD3 as a treatment target as an adjunct to systemic pancreatic cancer therapies." (PMID 39783776, 2025). "MRNA levels of AGR2, TFF1, and FXYD3 were greatly increased in pancreatic cancer cells when compared with non-cancerous cells." (PMID 39682235, 2024). "However, despite knowledge of its upregulation, the role of FXYD3 in pancreatic cancer survival has not yet been assessed on a larger scale." (PMID 39783776, 2025). "We have examined the effects of FXYD3-pep SKSK or FXYD3-pep CKCK on Dox-induced cytotoxicity in breast and pancreatic cancer cells that do or do not overexpress FXYD3." (PMID 35371992, 2022).
colorectal cancer (9 papers, 2011 to 2025). A primary or metastatic malignant neoplasm that affects the colon or rectum. "A study on a total of 150 resected colorectal cancer specimens measured the protein levels of FXYD3 by IHC staining and demonstrated an association of downregulated expression of FXYD3 proteins with cancer progression defined by Dukes’ staging." (PMID 34322151, 2021). "Upregulated FXYD3 expression appears to increase angiogenesis in hepatocellular carcinoma tumors and promotes oxaliplatin resistance in human colorectal cancer." (PMID 39682235, 2024). "Overexpression of FXYD3 in digestive tract tumors, including esophageal carcinoma and colorectal cancer, promoted tumor progression and an unfavorable prognosis." (PMID 34270462, 2021). "However, the expression feature of FXYD3 in colorectal cancer is controversial." (PMID 34270462, 2021). "Another study has demonstrated that the expression of FXYD3 was reduced in colorectal cancer cells with overexpression of DCLK1, thus representing a novel therapeutic target for colorectal cancer." (PMID 33350586, 2021). "Immunofluorescence signals for WT FXYD3 in MCF-7 cells partly overlap with signals for Na+/K+-ATPase α subunits, and a mostly perinuclear distribution of the β1 Na+/K+-ATPase subunits in cancer cells is also reported with the development of some colorectal cancers." (PMID 35371992, 2022).
lung carcinoma (8 papers, 2021 to 2024). "Another miRNA, let-7i, delivered by EVs in lung cancer cells limited tumor cell proliferation via the KDM3A/DCLK1/FXYD3 axis." (PMID 39063032, 2024). "Bioinformatic analysis tools were determinant to evaluate the role of a high expression of KDM3A (lysine demethylase 3A) and DCLK1 (doublecortin-like kinase 1) and reduced expression FXYD3 in lung cancer." (PMID 39769162, 2024). "A reduced expression of FXYD3 was reported in lung cancer cells, in which its inactivation was identified as a key player in lung cancer progression." (PMID 39769162, 2024). "In lung tumors, the increasing levels of DCLK1, promotes the proliferation and metastasis of lung cancer cells through the downregulation of FXYD3." (PMID 39769162, 2024). "The alternate promoter (AP) event identified in FXYD3 has been reported to be a significant overall survival predictor in lung cancer." (PMID 37924098, 2023). "Regarding airway disease, FXYD3 expression decreases during the transition from an airway epithelial cell to a lung cancer cell." (PMID 35993520, 2022). "In summary, our study provided evidence in support of the suppressive effects of BMSC‐EV‐derived let‐7i on the development of lung cancer cells through FXYD3 down‐regulation by increasing DCLK1 via KDM3A inhibition." (PMID 33350586, 2021). "Lastly, we found that the DCLK1 promotes the proliferation, migration and invasion of lung cancer cells through the inhibition of FXYD3." (PMID 33350586, 2021). "After loss‐ and gain‐of‐function assays, the effects of let‐7i, KDM3A, DCLK1 and FXYD3 on the biological characteristics of lung cancer cells were assessed." (PMID 33350586, 2021). "Collectively, these findings illustrated KDM3A as a tumour promoter in lung cancer through FXYD3 suppression by elevating DCLK1 via the removal of the methylation of H3K9me2 in the DCLK1 promoter region." (PMID 33350586, 2021). "Meanwhile, the poor expression of FXYD3 has been previously reported in lung cancer cells whereas its inactivation was identified as a potential player in lung cancer development." (PMID 33350586, 2021). "Particularly, the FXYD3 has been confirmed as a promising regulator in the progression of lung cancer." (PMID 33350586, 2021). "In conclusion, our findings demonstrated that the BMSC‐EV‐derived let‐7i possesses an inhibitory role in lung cancer progression through the KDM3A/DCLK1/FXYD3 axis, suggesting a new molecular target for lung cancer treatment." (PMID 33350586, 2021). "The expression of FXYD3 in lung cancer tissues and paracancerous tissues was measured with the application of RT‐qPCR, the findings of which showed a low expression of FXYD3 in lung cancer tissues." (PMID 33350586, 2021). "The findings showed the presence of a high expression of KDM3A and DCLK1 and reduced expression of let‐7i and FXYD3 in lung cancer." (PMID 33350586, 2021). "Hence, BMSC‐EV‐derived let‐7i was identified as an inhibitor of the pathogenesis of lung cancer by suppressing the DCLK1/FXYD3 axis through KDM3A." (PMID 33350586, 2021). "IHC results further demonstrated that FXYD3 was overexpressed in lung cancer tissues." (PMID 33350586, 2021). "BMSC derived-evs could suppress lung cancer via KDM3A/DCLK1/FXYD3 axis." (PMID 38105218, 2023). "Thus, we hypothesize that DCLK1 regulates the development of lung cancer by mediating the expression of FXYD3." (PMID 33350586, 2021). "Hence, DCLK1 could inhibit the FXYD3 and promote the proliferation, migration and invasion of lung cancer cells." (PMID 33350586, 2021). "The results showed that LET-7i derived from BMSC-EV suppressed the inhibitory effect of DCLK1 on FXYD3 by down-regulating the expression of KDM3A, thus inhibiting the proliferation, migration and invasion of lung cancer cells." (PMID 35860555, 2022).
lung carcinoma (continued). "detected the expression of let-7i, lysine demethylase 3A (KDM3A), bicorticoid kinase 1 (DCLK1) and ion transport regulator 3 (FXYD3) containing FXYD domain in lung cancer tissues, then determined the regulatory relationship among them, and observed the effects of them on lung cancer cells." (PMID 35860555, 2022). "Compared with cells transfected with si‐FXYD3, the expression of let‐7i and FXYD3 was enhanced in cells treated with si‐FXYD3 + EV‐mimic‐NC, the expression of KDM3A and DCLK1 was decreased, whereas the proliferation and invasion of lung cancer cells were inhibited, and the apoptosis was promoted." (PMID 33350586, 2021). "FXYD3 is expressed in human airway epithelia and is absent in lung cancer cells." (PMID 35993520, 2022).